BAX (BCL2 associated X, apoptosis regulator)
Diseases named in the same sentence as BAX in open-access papers (continued):
Sharing a sentence is not in itself a finding about the gene and the disease.
tumor (continued). "The upregulation of BAX and TNF expression in macrophages induces infiltration of aberrantly activated macrophages, which display dysfunctional differentiation in tumor tissues, altered immune responses, and activation of the tumor necrosis factor (TNF) pathway in UCEC macrophages." (PMID 39744500, 2025). "PTEN is a tumor suppressor gene while BCL2, BAX and Caspase 3 are apoptosis-related genes." (PMID 40457415, 2025). "In addition, M2 macrophages decreased the anti-tumor effects of vinorelbine by upregulating p-STAT3 and p-EGFR and downregulating BAX." (PMID 40076874, 2025). "Interestingly, compared to normal tissues, SPP1+ TAMs-CAFs regulated tumor cells through the regulation of genes related to HCC tumorigenesis, including CCND1, MYC, CTNNB1, and BAX." (PMID 40230843, 2025). "Notably, SGs sequester pro-apoptotic mRNAs, such as BAX and CASP3, inhibiting their translation while stabilizing the expression of anti-apoptotic proteins, including BCL2, to ensure the survival of tumor cells." (PMID 41029457, 2025). "This study emphasizes the promising clinical applications of targeting BAX and PLAU in tumor cells." (PMID 38988712, 2024). "Studies have shown that rosmarinic acid blocks the G2/S cycle in pancreatic carcinoma cells by adjusting the communication of cyclin E, BAX and Bcl-2; inhibits the migration and invasion of pancreatic cancer cells through E-cadherin and Matrix metallopeptidase 9 (MMP-9); and inhibits tumor growth." (PMID 38675663, 2024). "Furthermore, the results of IHC staining of tumor sections showed that the expression of Ki-67 and vimentin in CD36−/− mice was much lower than that in C57BL/6J mice, while BAX expression was higher in CD36−/− mice." (PMID 38319449, 2024). "We first compared the differences in protein expression of BAX, CASP1, CASP8 and PYCARD in renal clear cells by CPTAC database, and the results showed that the protein levels of BAX, CASP1, CASP8 and PYCARD were significantly higher than those in normal tissues in tumor cells." (PMID 38439022, 2024). "Second, due to the lack of detailed information on the patients, this study did not analyze the associations between BAX, BCL2 and c-MYC polymorphisms and gene expression and clinical features, such as tumor size and sensitivity to treatment." (PMID 38003498, 2023). "BAX and BCL-2 play important roles in regulating tumor growth." (PMID 36913356, 2023). "BAX is an apoptosis-promoting gene in the BCL-2 gene family, and its overexpression can antagonize the protective effects of BCL-2 and induce the apoptosis of tumor cells." (PMID 37280630, 2023). "The top-scoring genes altered in the four gene sets included many genes associated with cell apoptosis and DNA damage, such as GADD45A, DDIT3, BAX, CASP1, CASP8, ATM, and FANCD2, demonstrating that diminishment of RAD51 contributes to the tumor suppressive effect." (PMID 37175611, 2023). "In the present study, BDMC significantly inhibited the tumor growth of GBM 8401 xenograft mice in vivo via upregulating the expression of BAX (pro-apoptotic factor) and caspase-3 and downregulating the expression of Bcl-2 (anti-apoptotic factor) and XIAP in tumor tissues." (PMID 35008959, 2022). "However, tumor tissues of mice exposed to BDMC showed higher levels of cleaved caspase-3 and BAX (pro-apoptotic protein)." (PMID 35008959, 2022).
tumor (continued). "According to the expression levels and regression coefficients, the downregulated BAX, PWP2, SERTAD1, S1PR4, ZFAND1, NUDT13 and ZNF107 with HR < 1 were considered as tumor suppressors, whereas the MVD, BAD, CPNE7, CPNE7, UTP23 and ZNF124 upregulated with HR > 1 were regarded as oncogenes." (PMID 36685828, 2022). "Immunohistochemical staining for BCL-2, BAX and caspase-3 in tumour sections exhibited a marked decrease in BCL-2, Ki67 and pAKT and an increase in BAX and caspase-3 activity and expression in the tumours generated with ALKBH5- cells." (PMID 35414790, 2022). "Our in vitro results suggest that RP11-10A14.5 might inhibit tumor cell apoptosis through the regulation on expression of BAK, BAX and Caspase-3, which might enhance the metastatic cell survival." (PMID 35575835, 2022). "Treatment with EQ had evident anti-tumor effects on EAC as revealed by the remarkable decrease in the expression of the anti-apoptotic gene Bcl-2 and by a significant increase in the expression of apoptotic genes (BAX and caspase-3)." (PMID 34829755, 2021). "This treatment resulted in reduced tumor volume and weight, and induction of apoptosis with increased levels of BAX (BCL-2-like protein 4) and AIF (apoptosis-inducing factor) along with low levels of Mcl-1 (induced myeloid leukemia cell differentiation protein) and Bcl-2 (apoptosis regulator)." (PMID 34199169, 2021). "The initial reaction to inhibiting BAX and BAK as a treatment for neurological diseases of all kinds including neurodegenerative diseases such as ALS has been skepticism as BAX and BAK are predicted to be tumor suppressors." (PMID 33162554, 2021). "Autophagy is a key point on survival and tumor adaptation, whose inhibition decreases anti-apoptotic proteins’ expression (e.g. BCL-2 and survivin) or increases pro-apoptotic proteins, such as BAX, leading to tumor sensitization to photo-stress, e.g. 5-ALA-PDT." (PMID 33552982, 2020). "Finally, compared to macroH2A1 KD Huh-7 cells, FAK KD cells exhibited a significant reduction (p < 0.01) in the mRNA levels of tumor-promoting genes CCL2, EGF, BAX, KRT19, EGFR, NOTCH1, ABL1, and SMAD3." (PMID 33182805, 2020). "Finally, mechanism studies demonstrated that overexpression of CXCL8 in HepG2 cells regulates tumor-specific protein expression including ERK1/2, BAX and survivin." (PMID 32766720, 2020).
tumor (continued). "A total of 66 genes were differentially expressed between BAX-protected and non-protected tumors in non-tumor tissue and 47 genes in tumor tissue." (PMID 32486514, 2020). "Strikingly, a significant shift between the localizations of BAX and BAK is not apparent in non-tumor tissue, contrasting the differential BAX/BAK localizations in cultured cells." (PMID 32486514, 2020). "Therefore, relative BAX/BAK localization was measured in a cohort of HCC tumor isolates and corresponding non-tumor tissue." (PMID 32486514, 2020). "A total of 726 genes in the subgroup of BAX-protected tumors and 2029 genes in the subgroup of non-protected tumors showed differential regulation in tumor vs. non-tumorous tissue, effectively separating tumor from non-tumorous tissue in both groups." (PMID 32486514, 2020). "Additionally, the immunohistochemistry (IHC) staining of tumor sections revealed that SLMP53-2 decreased Ki-67 and VEGF, and increased BAX staining, compared to vehicle." (PMID 31405179, 2019). "Consequently, combined inhibition of ERK1/2 signalling and MCL1 is synthetic lethal, inducing profound, synergistic BAK/BAX-, BIM- and BMF-dependent apoptosis and tumour regression." (PMID 31727888, 2019). "Consequently, BRAF or MEK1/2 inhibitors are synthetic lethal with the MCL1 inhibitor AZD5991, driving profound tumour cell death that requires BAK/BAX, BIM and BMF, and inhibiting tumour growth in vivo." (PMID 31727888, 2019). "The tumor-suppressor miR-433 directly targets AKT3 and hence attenuates proliferation, cell viability and survival; the latter probably through downregulation of Bcl-2 and upregulation of BAX." (PMID 31752925, 2019). "Gene deletion studies in mice do not suggest a tumour suppressive role for BAX or BAK when knocked out individually (presumably due to their redundant roles) and double knockout results in perinatal lethality." (PMID 29769323, 2018). "We evaluated the expression levels of the following five genes associated with DNA damage, carcinogenesis, and/or chemoprevention mechanisms: the tumor suppressors ETV6 and PTEN, the cell death regulators BCL2 and BAX (anti- and proapoptotic, respectively), and the protooncogene ABL1." (PMID 30370304, 2018). "BAX and XIAP are important apoptosis-regulatory proteins, and cyclooxygenase-2 (COX2) is an inflammatory enzyme whose activity can inhibit the apoptosis of tumor cells." (PMID 30093972, 2018). "Given that our data implicates a central role for VDAC2 in promoting BAX-mediated apoptosis, we hypothesized that the BAX:VDAC2 interaction would also be important for the activity of BAX in tumor cells responding to chemotherapeutic agents." (PMID 30478310, 2018). "Although we did not observe a difference in the levels of the BAX protein in Western blot analyses, expression of pro-apoptotic BAX gene by tumor cells stimulated with CR-LAAO further demonstrated the potential of this enzyme as an apoptosis inducer." (PMID 28205610, 2017). "Previous reports have suggested that the tumor suppressive potential of YAP1 is due to its binding to TP73 and its regulation by RASSF1A leading to the expression of pro-apoptotic genes like BBC3/PUMA and BAX." (PMID 29179447, 2017). "The results of Western blot were consistent with the results of mRNA level, which fully demonstrated that CGOML can markedly reduce the tumor size by inducing in vivo apoptosis of MCF-7 cells by downregulating Bcl-2, and survivin expression and upregulating BAX expression." (PMID 27248325, 2016).
tumor (continued). "However, also in these tumor sublines, CX− cells with the lower mHsp70 expression showed an increased expression in Caspase 3/7, BAD and BAX compared to CX+ cells." (PMID 26197988, 2015). "Together, these results show that PCAF can induce cell apoptosis by modulating a GLI1/Bcl-2/BAX axis that in turn suppresses HCC progression, and suggest that 5-FU may exert a stronger anti-tumor effect in patients with PCAF expression in HCC tumors." (PMID 25855960, 2015). "Therefore, in addition to tumor extent and TNM stage that were confirmed as significant predictors of DFS (P = 0.046 and P < 0.001, respectively), BAX gene expression at the mRNA level was shown to predict longer DFS in NPC." (PMID 23777485, 2013). "More importantly, BAX mRNA expression retained its independent prognostic significance in NPC (HR = 0.36, 95% CI = 0.16–0.84, P = 0.018) even when the multivariate Cox regression model was adjusted for patients’ gender, age, tumor histology, and TNM stage." (PMID 23777485, 2013). "Perhaps even more important was the finding that NPC patients without distant metastases are less likely to relapse when their tumor is BAX mRNA-positive, compared to metastasis-free patients with a BAX-negative nasopharyngeal malignancy." (PMID 23777485, 2013). "BAX expression was absent in 50% of the tumours, whereas BAK was expressed in all the samples (100%)." (PMID 23762382, 2013). "As the transcription of apoptosis related genes could help to elucidate the pathogenesis of tumours, we propose to investigate the quantitative expression of BCL-2 (anti-apoptotic), BAX and Caspase3 (pro-apoptotic genes) using qPCR." (PMID 22313995, 2012). "Unexpectedly however neither BAX single KO or BAX/BAK double KO show increased tumour formation suggesting that compensatory mechanisms can allow apoptosis in these cells." (PMID 22683550, 2012). "These antigenic epitopes could be good candidates for immunotherapy, because mutations in the MSH3 gene, along with others, e.g. TGFβRII, BAX and MSH6, appear to play an active role in tumor progression." (PMID 22110587, 2011). "BAX or Bcl-2 was correlated with a higher degree of differentiation or left-sided tumours (P=0.01 or P=0.03, respectively); MSI was correlated with right-sided tumours (P<0.0001)." (PMID 17426704, 2007). "We analyzed the expression of tumor-related markers, including VEGF (a key pro-angiogenic factor), and apoptotic genes, BAX (pro-apoptotic) and BCL2 (anti-apoptotic), to assess whether dynamic culture within the BAF bioreactor would alter the tumorigenic characteristics of SAOS-2 cells." (PMID 41439917, 2025). "Furthermore, upon treating various types of tumour cell lines with FOXO1 inhibitors, we observed not only the upregulation of VEGFC, PD‐L1 and CCL4 but also varying degrees of increase in MOMP‐related molecules (such as BAX, BAK1, CASP3, STING, IRF3 and RELB)." (PMID 38899748, 2024). "Additionally, treatment with p28 with or without iRGD and 5-FU significantly enhanced the level of BAX while decreasing the level of BCL2 in the tumor tissue, which increases the ratio of apoptosis (P<0.01 and P<0.001, respectively)." (PMID 37396945, 2023). "Similarly, we sorted primary Ph− B-ALL cells with C-MYC overexpression and without BAX deletion to construct a B-ALL patient-derived tumor xenograft (PDX) model." (PMID 36765389, 2023). "To understand the mechanism of this differential effect, we found that ferroptosis inducers upregulate mRNAs encoding multiple direct and indirect autophagy stimulators, such as ATG16L2, ATG9A, ATG4D, GABARAP, SQSTM/p62, SEC23A and BAX, in tumor cells growing in 2D but not in 3D culture." (PMID 37658069, 2023). "We also examined the protein level of tumor tissues in two groups, which showed that PHGDH and pathway-related indicators β-catenin, c-myc, cyclin D1, PCNA, Bcl2, N-cadherin, vimentin, and Snail expression level were lower and BAX and E-cadherin higher in CBR-5884 group." (PMID 36105480, 2022).
tumor (continued). "However, compared with the tumor areas, BAX immunostaining was quite minimal in non-tumorous areas of HCC or DM-treated HCC rat livers." (PMID 36313224, 2022). "However, the BAX protein expression in SH-SY5Y cells after the triple co-culture was higher than in the tumor cells after the double co-culture, which indicates a cytotoxic influence of a number of PBMCs on tumor cells in the triple co-culture." (PMID 36354566, 2022). "BAX might be related to DLBCL proliferation and inhibiting tumor cell proliferation." (PMID 36213322, 2022). "Indeed, glioma oncolysis is significantly reduced when Beclin-I (autophagy inducer) is downregulated in tumor cells, and tamoxifen drug, upon activation of apoptosis in OV infected cells via BAX/PUMA pathway, is able to re-establish the tumor sensitivity to oncolytic infection." (PMID 34163465, 2021). "BID played a similar role by activating BAX/BAK 25 and ERBB2, also known as HER2, was a member of the human epidermal growth factor receptor family, promoting cell proliferation, survival, and playing an important role in the occurrence and development of tumor." (PMID 32780567, 2020). "In this study, we found that the tumor suppressor miR-34c was inhibited by NEAT1 in OS, and restoration of miR-34c could abrogate NEAT-1-induced proliferation and inhibition of apoptosis via regulation of the balance between BCL-2 and BAX." (PMID 29654165, 2018). "To establish whether the increased expression of pro-apoptotic BAX protein and simultaneous reduction of anti-apoptotic proteins Bcl2 and Bcl-XL in CMLD-2-treated tumor cells occurred through apoptosis, we performed western blot analysis for apoptotic proteins." (PMID 28855578, 2017). "Therefore, we propose PATZ1 as a new prognostic marker of DLBCLs, which may act as a tumor suppressor by enhancing apoptosis through inhibiting and enhancing transcription of BCL6 and BAX, respectively." (PMID 27494852, 2016). "Delivery of BAX mRNA by lipofectamine did not significantly inhibit tumor growth." (PMID 24073264, 2013). "Furthermore, NPC patients without distant metastases are less likely to relapse when their primary tumor is BAX mRNA-positive, compared to metastasis-free patients with a BAX-negative nasopharyngeal malignancy." (PMID 23777485, 2013). "However, the overall tumor response to 17-AAG is dominated by the cytostatic antiproliferative effect that is independent of BAX status." (PMID 24185264, 2013). "In contrast, and entirely consistent with our earlier in vitro findings, induction of apoptosis by 17-AAG was observed in HCT116 BAX+/− but not in HCT116 BAX−/− tumor xenografts as measured by the cleavage of caspase-3 on day five following daily i.p doses of 80mg/kg 17-AAG." (PMID 24185264, 2013). "In contrast, CDDP-treatment of pxn65 tumours did not significantly alter BAX and BAK expression." (PMID 15452549, 2004). "Also, differences between event-free survival curves of patients with BAX positive and BAX negative tumours were not statistically significant." (PMID 11875737, 2002). "Additionally, a report on tumor and non-tumor tissues extracted from patients with hepatocellular carcinoma showed that the expression of HSPB6 was elevated in the non-tumor tissues compared to the tumor tissues, and it has a direct link with BAX to regulate apoptosis." (PMID 37241227, 2023).